CPLANE1 (ciliogenesis and planar polarity effector complex subunit 1)
Description:
Involved in ciliogenesis. Involved in the establishment of cell polarity required for directional cell migration. Proposed to act in association with the CPLANE (ciliogenesis and planar polarity effectors) complex. Involved in recruitment of peripheral IFT-A proteins to basal bodies (By similarity).
Synonyms: C5orf42; JBTS17; FLJ13231; Hug; OFD6
Tractability: Antibody: UniProt predicts a signal peptide or a membrane-spanning region. PROTAC: ubiquitination databases record sites on it.
Gene: Protein-coding gene on chromosome 5 (37,106,228 to 37,249,400, reverse strand). Ensembl gene ENSG00000197603.
Subcellular location: Membrane; Cell projection, cilium
Subcellular location (Human Protein Atlas): Cytosol; Mid piece; Principal piece
Gene Ontology:
Biological process: cilium assembly
Cellular component: ciliary transition zone; cilium; membrane
Genetic constraint (gnomAD): Loss-of-function variants: 180 observed, 279.89 expected, observed/expected ratio (o/e) 0.64, 90% interval 0.57 to 0.73. The upper end of that interval is the gene's LOEUF score, 0.73, which puts it in group 2 of 6, group 1 being the genes least tolerant of losing a copy. Missense variants: 2,888 observed, 3,319.4 expected, observed/expected ratio (o/e) 0.87, 90% interval 0.84 to 0.9. Synonymous variants: 1,049 observed, 1,161.4 expected, observed/expected ratio (o/e) 0.9, 90% interval 0.86 to 0.95.
Gene-disease validity (ClinGen):
ClinGen rates the evidence that CPLANE1 causes each of these diseases.
Joubert syndrome 17 (autosomal recessive): Definitive. Any Joubert syndrome in which the cause of the disease is a mutation in the CPLANE1 gene.
Homologues: Orthologues: chimpanzee CPLANE1 (97% identical), macaque CPLANE1 (95% identical), dog CPLANE1 (77% identical), pig CPLANE1 (74% identical), rabbit CPLANE1 (72% identical), rat Cplane1 (67% identical), mouse Cplane1 (65% identical), tropical clawed frog CPLANE1 (39% identical).
Diseases named in the same sentence as CPLANE1 in open-access papers:
CPLANE1 is named in the same sentence as 41 diseases in open-access papers, as found by Europe PMC text mining. Sharing a sentence is not in itself a finding about the gene and the disease. The quoted sentences say what the papers report.
Joubert syndrome (17 papers, 2015 to 2025). Joubert syndrome (JS) is characterized by congenital malformation of the brainstem and agenesis or hypoplasia of the cerebellar vermis leading to an abnormal respiratory pattern, nystagmus, hypotonia, ataxia, and delay in achieving motor milestones. "Given the proband's maternal history of three similar adverse pregnancies, with carrying novel compound heterozygous variants in CPLANE1, these variants were strongly suspected to be the underlying cause of fetal Joubert syndrome." (PMID 40074699, 2025). "In this study, we identified novel compound heterozygous variants in CPLANE1, c.8893C>T (p.Gln2965*) and c.203C>T (p.Thr68Ile), in a family with recurrent fetal abnormalities indicative of Joubert syndrome (JS)." (PMID 40074699, 2025). "In this paper, we report a proband from a Han Chinese family with both CPLANE1-Joubert syndrome and X-linked Klinefelter syndrome, as well as the keratoconus phenotype." (PMID 39076169, 2024). "Trio-based WES was performed on both parents and the affected fetus, revealing a pair of compound heterozygous CPLANE1 variants (c.4646 A > T/p.Glu1549Val and c.1233 C > A/p.Tyr411*) potentially associated with Joubert syndrome." (PMID 39725884, 2024). "Our findings suggest that CPLANE1 variants are more likely to cause KC-Joubert syndrome by affecting the function of the CPLANE1-NPHP3 complex protein, which is considered to act as a bridge between cilia and extracellular matrix (ECM) tissue." (PMID 39076169, 2024). "Taken together, these novel compound heterozygous frameshift variants in CPLANE1 are more likely to cause KC-Joubert syndrome by affecting the function of the CPLANE1 protein." (PMID 39076169, 2024). "The CPLANE1 variants associated with Joubert syndrome collected by ClinVar include 37 frameshift mutations, 153 missense mutations, 28 nonsense mutations, 13 splicing site variants, and 25 untranslated region (UTR) variants." (PMID 39076169, 2024). "Biallelic variants in the CPLANE1 gene (OMIM* 614571) have been reported to cause Joubert syndrome (JS, OMIM# 614615), a rare disorder characterized by a peculiar cerebellar and brainstem malformations known as molar tooth sign (MTS)." (PMID 39725884, 2024). "Variants or deletions of CPLANE1 are closely related to a variety of defects, among which the CPLANE1 variant is a common cause of Joubert syndrome." (PMID 35582950, 2022). "MD-307 and MD-216 (CPLANE1 p.S1127A/c.7588+3A>G) presented the characteristic molar tooth sign on brain MRI associated with Joubert syndrome." (PMID 36233161, 2022). "In the past, it was thought that CPLANE1 interacted with the NPHP1 gene in the primary ciliary transition region to cause the occurrence of Joubert syndrome." (PMID 35582950, 2022). "Dysfunction of Jbts17 (also known as CPLANE1), a gene mutated in Joubert syndrome, Meckel syndrome, and oral-facial-digital syndrome, causes ciliogenesis and ciliary trafficking defects, and results in decreased Shh target gene expression." (PMID 31781166, 2019). "The expression patterns of CPLANE1 and the molecular effects of the variants may provide further evidence supporting the potential for prenatal diagnosis of Joubert syndrome in the case of biallelic VUS and pathogenic variant." (PMID 39725884, 2024). "In this study, we report a proband in a Han Chinese family with both Joubert syndrome and X-linked Klinefelter syndrome as well as keratoconus, and the phenotype spectrum of CPLANE1-Joubert syndrome may be expanded accordingly." (PMID 39076169, 2024). "The CPLANE1 variant causes an abnormal number of primary cilia, which affects the Hh signalling pathway transduced by the primary cilia, leading to the occurrence of Joubert syndrome." (PMID 35582950, 2022). "Joubert syndrome (JBTS) is a class of heterogeneous ciliopathy genetically associated with CPLANE1 mutations." (PMID 36789003, 2023).
Joubert syndrome (continued). "For example, the GDR CPLANE1 and Joubert syndrome 17 was shared between the SD-GCEP from the Kidney Cystic and Ciliopathy Disorders (KCCD) GCEP because of overlapping phenotypes." (PMID 40496713, 2025). "The following diseases were found in two or more cases: Joubert syndrome (IFT74/CPLANE1, n = 2) and Noonan syndrome (PTPN11/KRAS, n = 3)." (PMID 37895220, 2023). "In contrast, the Joubert syndrome cluster contained five hits found under starved conditions, CPLANE1, UNC119, PIBF1, and CEP164." (PMID 34685691, 2021). "The phenotype spectrum of CPLANE1-Joubert syndrome may be expanded accordingly." (PMID 39076169, 2024).
ciliopathy (13 papers, 2015 to 2026). A genetic disorder of the cellular cilia or the cilia anchoring structures, the basal bodies, or of ciliary function. "Recent reports have linked the CPLANE1 gene with ciliopathy, including a mild phenotype of JS and OFDS." (PMID 41552241, 2025). "Our study expands the known pathogenic variant spectrum of CPLANE1 in JS and provides new insights into the molecular mechanisms of this ciliopathy." (PMID 40074699, 2025). "The addition of other ciliopathy genes (such as CPLANE1 for JBTS) would, of course, further increase diagnostic yield." (PMID 35764379, 2022). "Based on these findings and our results implicating the ciliopathy gene CPLANE1 (also termed C5ORF42 or JBTS17) in axon guidance, we tested whether primary cilium-mediated signaling was required for Shh-dependent commissural axon guidance." (PMID 39157903, 2024).
Joubert syndrome type 17 (3 papers, 2024 to 2025). "CPLANE1 gene variants are associated with Joubert syndrome type 17 (OMIM:614615) and oral‐facial‐digital syndrome type 6 (OMIM:277170), both inherited in an autosomal recessive (AR) pattern." (PMID 40074699, 2025).
Orofaciodigital syndrome VI (3 papers, 2021 to 2024). "Damaging variants in CPLANE1 can cause JS or more frequently, orofaciodigital syndrome VI (OFD6)." (PMID 38003592, 2023).
developmental delay (2 papers, 2015 to 2025). "CPLANE1 mutations cause JS type 17, which manifests with cerebellar ataxia, developmental delay, and polydactyly." (PMID 40074699, 2025).
Nephropathy (2 papers, 2023 to 2024). A nonspecific term referring to disease or damage of the kidneys. "Renal disease can occur in as many as 1/3 of JS patients, but renal disease is less likely in JS patients with CPLANE1 variants." (PMID 39076169, 2024).
polydactyly (2 papers, 2018 to 2022). A disease characterized by the presence of polydactyly, including syndromic and non-syndromic forms. "More significantly, in a large cohort of 313 JS individuals mainly of Italian origin, 27 out of 28 patients carrying biallelic variants in CPLANE1 manifested an exclusively neurological phenotype, although polydactyly was a common associated feature." (PMID 35238134, 2022).
breast carcinoma (1 paper, 2025). "We have also characterized the molecular profile of PNI-competent breast cancer cells and showed that CPLANE1 and hemopexin are potential markers for PNI-competent breast cancer cells." (PMID 40628700, 2025). "We found that CPLANE1 is upregulated in PNI-competent breast cancer cells." (PMID 40628700, 2025).
cephalocele (1 paper, 2025). A congenital neural tube closure defect resulting in the protrusion of the brain through a skull opening. "Owing to the high level of consanguinity in our society, JS is not uncommon; we have identified one more local patient with JS due to the CPLANE1 gene, but without the presence of a cephalocele or Dandy-Walker variant or a cephalocele." (PMID 41552241, 2025). "Although the association of Joubert-Plus syndrome with cephalocele was described in the literature, none of the reports described the association with Dandy-Walker malformation, occipital cephalocele, or Joubert-Plus syndrome caused by the CPLANE1 gene mutation." (PMID 41552241, 2025).
Cerebellar hypoplasia (1 paper, 2023). Cerebellar hypoplasia is a descriptive term implying a cerebellum with a reduced volume, but a normal shape and is stable over time. "Seven probands carry causative variants in well-known genes associated with CA or cerebellar hypoplasia: SETX, CACNA1G, CACNA1A, CLN6, CPLANE1, and TBCD." (PMID 38003592, 2023).
Exotropia (1 paper, 2024). A form of strabismus with one or both eyes deviated outward. "In this study, novel compound heterozygous frameshift variants M1: c.9279dup:p.H3094Tfs*18 and M2: c.6515_6522del:p.K2172Tfs*37 were detected in the CPLANE1 gene of the proband, who had ocular phenotypes of keratoconus, exotropia, ptosis, and JS-related signs." (PMID 39076169, 2024).
keratoconus (1 paper, 2024). A degenerative, structural disorder of the eye, characterized by a cone-shaped protrusion of the cornea. "Differential expression analysis of keratoconus-related genes showed that CPLANE1 was upregulated in the corneal tissues of keratoconus patients compared with normal controls, and such a difference was statistically significant (p = 0.000515, <0.05)." (PMID 39076169, 2024).
leukoplakia (1 paper, 2022). A white patch or plaque on a mucous membrane that cannot be characterized clinically or pathologically as any other disease. "The role of ciliogenesis and planar polarity effector 1 (CPLANE1) has been analyzed in patients with OSCC, patients with potentially malignant disorders (leukoplakia and lichen planus without distinguishing between these pathologies, and healthy subjects." (PMID 36330456, 2022).
situs inversus (1 paper, 2021). A congenital condition in which there is complete right-to-left reversal of the position of the major thoracic and abdominal organs (that is, they are arranged in a mirror image of the normal positioning). "Situs inversus caused by CPLANE1 variant was first reported." (PMID 34675960, 2021).
tumor (5 papers, 2022 to 2025). "We then examined the mRNA levels of CPLANE1 and hemopexin in a small cohort of PNI+ and PNI- tumor samples and found significant upregulation of CPLANE1 in PNI+ cases, validating the proteomics results." (PMID 40628700, 2025). "Although gene expression analysis in OPMD tissues was limited by the small sample size available from diagnostic biopsies, we employed the Gene Expression database of Normal and Tumor tissues 2 (GENT2) to objectively evaluate tissue expression levels for CPLANE1 and CCL20." (PMID 40869423, 2025). "Interestingly, while LPS treatment increased the proliferation and expression of the GEN1, KRIT1, CENPF, CPLANE1, STYK1, and KHDRBS3 genes, it decreased the expression of the cancer associated LOC610994, Gpatch4, SLC7A1, ATP13A2, and TEX45 genes in tumor enteroids." (PMID 35884586, 2022). "Among the proteomic markers, elevated levels of serum ceruloplasmin, MYO1B, salivary CPLANE1, serum albumin, HSP 27, gamma actin, SCC 1, and A4, serum SNCG and SCCAg and immune cell markers such as, IL‐6, TNF‐α, and CD4 + T cell were suitable proteomic tumor markers in detecting OSCC." (PMID 40256126, 2025).
CPLANE1 also shares sentences with these, for which no sentence is quoted: Hamartoma of tongue (2 papers); acrocallosal syndrome (1); Bardet-Biedl syndrome (1); cancer (1); cerebellar ataxia (1); Dandy-Walker malformation (1); diabetes (1); heart failure (1); hypothalamic hamartoma (1); Intellectual disability (1); Kidney Cystic (1); lichen planus (1); Meckel syndrome (1); neurodevelopmental disorder (1); Noonan syndrome (1); oral-facial-digital syndrome (1); Polysyndactyly (1); ptosis (1); renal failure (1); retinal diseases (1); schizophrenia (1); Senior-Loken syndrome (1); skeletal dysplasia (1); Strabismus (1); Usher syndrome (1); xeroderma pigmentosum (1).